RLN3 (relaxin 3)
Description:
May play a role in neuropeptide signaling processes. Ligand for LGR7, RXFP3 and RXFP4.
Synonyms: INSL7; RXN3; ZINS4; H3
Tractability: Antibody: its Gene Ontology location is reachable by antibodies, with high confidence; UniProt places it where antibodies can reach, with medium confidence; UniProt predicts a signal peptide or a membrane-spanning region.
Gene: Protein-coding gene on chromosome 19 (14,028,148 to 14,031,551, forward strand). Ensembl gene ENSG00000171136.
Subcellular location: Secreted
Pathways (Reactome):
Signal Transduction: G alpha (i) signalling events; G alpha (s) signalling events; Relaxin receptors
Gene Ontology:
Molecular function: protein binding; G protein-coupled receptor binding; hormone activity
Biological process: signal transduction
Cellular component: extracellular region
Genetic constraint (gnomAD): Loss-of-function variants: 14 observed, 11.6 expected, observed/expected ratio (o/e) 1.21, 90% interval 0.79 to 1.79. The synonymous counts are far from expectation, so gnomAD's model fits this gene poorly and the ratio says little. Missense variants: 191 observed, 192.87 expected, observed/expected ratio (o/e) 0.99, 90% interval 0.88 to 1.12. Synonymous variants: 56 observed, 82.79 expected, observed/expected ratio (o/e) 0.68, 90% interval 0.55 to 0.85.
Homologues: Orthologues: chimpanzee RLN3 (98% identical), macaque RLN3 (91% identical), pig RLN3 (79% identical), mouse Rln3 (78% identical), dog RLN3 (77% identical), rat Rln3 (75% identical), rabbit RLN3 (70% identical), guinea pig RLN3 (59% identical), zebrafish rln3b (45% identical), tropical clawed frog rln3 (40% identical), zebrafish rln3a (39% identical). Paralogues in human: INSL5 (25% identical).
Diseases named in the same sentence as RLN3 in open-access papers:
RLN3 is named in the same sentence as 25 diseases in open-access papers, as found by Europe PMC text mining. Sharing a sentence is not in itself a finding about the gene and the disease. The quoted sentences say what the papers report.
Anxiety (16 papers, 2012 to 2024). Intense feelings of nervousness, tension, or panic often arise in response to interpersonal stresses. "Our outcomes of interest in this association study include depression, atypical depression, anxiety and metabolic syndrome, each of which has previously been linked to the relaxin-3/RXFP3 across the pertinent literature of animal studies." (PMID 37967073, 2023). "Relaxin-3 neurons located in the midbrain, and pons were associated with dysfunctional modalities (e.g., stress, arousal, anxiety) in neuropsychiatric diseases." (PMID 36004833, 2022). "The association to anxiety and depression was discovered as RLN3 expressing neurons also express inhibitory serotonin type 1A (5-HT1A) receptors, suggesting functional interactions between these two systems." (PMID 31794429, 2019). "Long-lasting, stress-induced adaptations to alcohol drinking behaviour have been reported in mice and relaxin-3/RXFP3 signalling is implicated in the regulation of chronic anxiety associated with prior stress exposure." (PMID 25849482, 2015). "Interestingly, RLN3 is an insulin-like peptide and has been shown to control multiple disease processes linked to aging mechanisms, e.g., anxiety, depression, memory dysfunction, appetite, and anti-apoptotic mechanisms." (PMID 35457203, 2022). "Notably, a distinct population of GABAergic NI neurons expresses the highly-conserved neuropeptide, relaxin-3, and relaxin-3 signaling has been implicated in the modulation of reward/motivation and anxiety- and depressive-like behaviors in rodents via actions within the extended amygdala." (PMID 27092060, 2016). "A number of studies have found that aversive stimuli promote expression of c-Fos in the NI, leading researchers to evaluate the role of relaxin-3 in anxiety-like behaviors." (PMID 38819436, 2024). "The relaxin-3/RXFP3 system has been implicated in the modulation of depressive- and anxiety-like behaviour in the animal literature; however, there is a lack of human studies investigating this signalling system." (PMID 37967073, 2023). "Previous studies have shown that the cognate ligand of RXFP3, relaxin-3, plays regulatory roles in appetite, arousal, memory, stress, anxiety and depression, thereby making this receptor an attractive target for drug discovery." (PMID 34946593, 2021). "RXFP3 has been implicated in stress response, anxiety, depression, feeding, arousal and alcohol addiction using RXFP3/RLN3 deficient mouse models." (PMID 31794429, 2019). "Apart from the Relaxin-3 distribution, behavioral data suggest that Relaxin-3 has a role in stress/anxiety, cognition and appetite regulation." (PMID 22347403, 2012). "We investigated the effects of reduced relaxin-3 on body weight, food and water intake, plasma glucose and paradigms related to locomotor activity, spatial learning and memory and anxiety." (PMID 22876314, 2012). "In rodents the RLN3/RXFP3 signaling system, with RLN3 neurons originating in the NI, has been implicated in the control of food intake, stress responses (including freezing), anxiety, addiction, locomotor activity, memory, and other arousal-related behaviors." (PMID 36277494, 2022). "Similarly, RLN3 influences feeding behavior, stress responses, anxiety and memory, and AVP is a regulator of social behavior." (PMID 33834688, 2021). "This is the first study to evaluate candidate SNPs pertinent to the relaxin-3/RXFP3 system in the context of depression, anxiety and atypical depression, and the first to assess a relationship with metabolic parameters using a rigorous statistical approach." (PMID 37967073, 2023). "Recently, therapy of anxiety, depression, and related disorders in rats was targeting the RLN-3/RXFP3 system via intranasal delivery of an RLN-3 mimetic with positive results." (PMID 36004833, 2022).
Anxiety (continued). "Intracerebroventricular (icv) infusions of relaxin-3 and selective RXFP3 agonists in rat activate PVN CRF neurons and the HPA axis, and modulate anxiety and depressive-like behaviour, respectively." (PMID 25849482, 2015). "The conserved tissue distributions of relaxin-3 and RXFP3 together with behavioral data from animal studies suggest that relaxin-3 has roles in stress/anxiety, cognition and appetite regulation." (PMID 24349312, 2013). "Overall, this suggests that RXFP3 is involved in the central processing of sensory signals and supports the possible modulatory role of the relaxin-3/RXFP3 system in stress and anxiety, feeding and metabolism and arousal and behavioural activation." (PMID 22876314, 2012). "Previous studies have suggested a role for the neuronal relaxin-3/RXFP3 system in feeding and metabolism, behavioural activation and arousal and anxiety-like behaviour and the stress response." (PMID 22876314, 2012). "Given the role identified for the relaxin-3/RXFP3 system in the MS and the generation of hippocampal theta rhythm, it was important to assess the anxiety of rats following administration of rAAV1/2 EmGFP miR499." (PMID 22876314, 2012). "The tissue distribution and function of Relaxin-3 and RXFP3 indicate potential therapeutic application of RXFP3 modulators to treat stress/anxiety, cognitive disorders and metabolic diseases." (PMID 22347403, 2012). "A novel study on female rats with mRNA-induced RLN-3 depletion led to alterations in food intake, a 2% decrease in body weight, and increase in anxiety-like behavior, although only in a large open field but not in an elevated plus-maze or light/dark box." (PMID 36004833, 2022). "Here, we review published experimental data on relaxin-3/RXFP3 systems in rodents, and attempt to highlight aspects that are relevant and/or potentially translatable to the etiology and treatment of major depression and anxiety." (PMID 24711793, 2014). "In this subgroup, there was a lack of correlation between relaxin-3 mRNA and behaviour in any paradigm used to assess energy balance, locomotor activity, spatial working memory or anxiety." (PMID 22876314, 2012). "It is important to recognise that a lack of significant associations in this candidate gene study does not rule out a role for the relaxin-3/RXFP3 system in MDD, atypical depression, anxiety or metabolic syndrome." (PMID 37967073, 2023).
depression (6 papers, 2014 to 2023). "In this regard, characterizing the potential involvement of novel transmitter systems such as relaxin-3 in the etiology of depression will be of interest." (PMID 24711793, 2014). "Although research in this area is still in its relative infancy, several key features have highlighted relaxin-3/RXFP3 systems as an attractive putative target for the treatment of cognitive deficits, and neuropsychiatric disorders, including depression." (PMID 24711793, 2014). "Before correction for multiple testing, rs74400983 (unadjusted p = 0.0232) and rs78161395 (unadjusted p = 0.0428) at RLN3, as well as rs62351166 (unadjusted p = 0.0388) at RXFP1 were nominally linked with the broad phenotype of depression; however, these did not withstand FDR corrections." (PMID 37967073, 2023).
Obesity (4 papers, 2010 to 2022). Accumulation of substantial excess body fat. "Interestingly, a polymorphism within the RXFP3 gene was significantly associated with obesity, while one polymorphism in the relaxin-3 gene and two in the RXFP3 gene were significantly associated with hypercholesterolemia." (PMID 24711793, 2014). "Given these associations, considerable activity has since focused on the development of RLN3-based interventions for obesity paradigms." (PMID 35457203, 2022). "With respect to the links between the RLN3/RXFP3 system and human obesity it has been shown that RLN3 genetic polymorphisms are significantly associated with traits including obesity, hypercholesterolemia, and diabetes." (PMID 35457203, 2022). "The intersection of RLN3/RXFP3 signaling between stress-responsive binge eating and this greater role of RXFP3 in predisposition to obesity demonstrates the importance of this system in the control of glucometabolic dysfunction in the aging context." (PMID 35457203, 2022). "The polypeptide/small protein human relaxin-3 92, an insulin-like peptide which is also known as insulin-like peptide 7 (INSL7), is involved in neurological stress responses and effects on food intake, thus making it a potential drug for treatment of obesity and stress." (PMID 20877250, 2010).
mental disorder (3 papers, 2014 to 2021). A disease that has its basis in the disruption of mental process. "Therefore, previous reviews of the neurobiology of the NI and its relaxin-3 signaling system have focused on a likely role in stress and arousal, feeding behavior, and a possible involvement in mental illnesses with a summary of associated relaxin-3 signaling via RXFP3." (PMID 33867946, 2021). "Further studies of any potential involvement of relaxin-3 in the etiology of neurological or psychiatric diseases are also warranted (c.f.Lin and Sibille, 2013)." (PMID 24711793, 2014).
breast carcinoma (2 papers, 2014 to 2024). "Additionally, we show in an ex vivo model of metastatic brain colonization that porcine relaxin as well as human brain-specific relaxin-3 promotes invasion into the brain tissue and enhance interaction of breast cancer cells with the resident brain macrophages, the microglia." (PMID 23963762, 2014).
diabetic cardiomyopathy (2 papers, 2020 to 2023). Diabetic cardiomyopathy is a disorder of the heart muscle in people with diabetes. "Relaxin-3 is a bioactive peptide with a structure similar to insulin, which has been reported to be effective in diabetic cardiomyopathy models in vivo and in vitro." (PMID 33584279, 2020).
eating disorder (2 papers, 2020 to 2023). A broad group of psychological disorders with abnormal eating behaviors leading to physiological effects from overeating or insufficient food intake. "The RLN3 gene is thought to be involved in eating disorders in humans and mice." (PMID 37510415, 2023).
hepatocellular carcinoma (2 papers, 2021 to 2022). A malignant tumor that arises from hepatocytes. "RLN3 is implicated in the prognosis of hepatocellular carcinoma (HCC)." (PMID 33413474, 2021).
asthma (1 paper, 2022). "On the other hand, relaxin-3 has antifibrotic effect by inhibiting growth factors and seems to reverse the fibrosis process in the airways of a mouse model of asthma." (PMID 36312895, 2022).
binge eating disorder (1 paper, 2020). Recurrent episodes of over-eating. "Notably, higher intra- and peri-PVN RLN3 fiber densities were observed in females, which may constitute an anatomic substrate for observed sex differences in binge-eating disorder." (PMID 32532885, 2020).
cognitive deficits (1 paper, 2014). "It is possible, however, that modulation of endogenous relaxin-3/RXFP3 signaling might reduce the severity of the negative affective symptoms and cognitive deficits displayed in schizophrenic patients." (PMID 24711793, 2014).
lung adenocarcinoma (1 paper, 2023). A carcinoma that arises from the lung and is characterized by the presence of malignant glandular epithelial cells. "In lung adenocarcinoma, the immune stemness genes Interleukin-6 (IL-6), Formyl peptide receptor 2 (FPR2) and Relaxin-3 (RLN3) can play an important role in tumor development through cytokine-cytokine receptor interactions and neuroactive ligand-receptor interactions." (PMID 38037058, 2023).
male infertility (1 paper, 2025). The inability of the male to effect fertilization of an ovum after a specified period of unprotected intercourse. "Also, the Rln3 seems to play a significant role during Nile tilapia (Oreochromis niloticus) spermatogenesis, since mutations in rln3a and rln3b result in male infertility." (PMID 40530338, 2025).
cancer (2 papers, 2020 to 2024). A tumor composed of atypical neoplastic, often pleomorphic cells that invade other tissues. "Third, protein interaction networks of unique DEGs of the two voles relabeled that among the severe hypoxia-specific DEGs in L. mandarinus, the most prominent core genes were RLN3, AVP, CALCA, and SOX2, which regulate responses to stress, metabolism, and cancer." (PMID 32256671, 2020).
tumor (2 papers, 2014 to 2023). "We then asked whether relaxin-3 exerts its effect via its specific receptor RXFP3 or via RXFP1 in both tumour cells and brain." (PMID 23963762, 2014).
neurological diseases (1 paper, 2013). "Relaxin-3 is involved in a wide range of behaviors, including feeding, stress responses, arousal, and cognitive processes and therefore targeting of RXFP3 may be relevant for a range of neurological diseases." (PMID 23440673, 2013).
RLN3 also shares sentences with these, for which no sentence is quoted: Cirrhosis (1 paper); colorectal cancer (1); dementia (1); diabetes (1); head and neck cancer (1); Hypercholesterolemia (1); metabolic syndrome (1); middle cerebral artery (1); Zinc deficiency (1).